IL32 (interleukin 32)
Diseases named in the same sentence as IL32 in open-access papers (continued):
Sharing a sentence is not in itself a finding about the gene and the disease.
type 1 diabetes (8 papers, 2021 to 2025). "IL-32 was found to be upregulated by activated T cells and NK cells before the appearance of autoantibodies typically associated with type 1 diabetes." (PMID 41340965, 2025). "In the CD8+ T cells, we validated the DMC near IL32 (chr16:3116115), which was hypomethylated on the promoter region in type 1 diabetes, compared with control participants." (PMID 35142878, 2022). "We demonstrated that cytokine-treated SC-organoids secrete IL-32, which is considered a promising candidate for type 1 diabetes onset." (PMID 35122482, 2022). "More recently, IL-32 is also involved in type 1 diabetes; its mRNA levels in beta-cells were higher than in those in control subjects." (PMID 35281066, 2022). "In any case, further studies on the role of IL-32 in the development of type 1 diabetes would be worthwhile." (PMID 35122482, 2022). "A potential role for IL-32 in type 1 diabetes has been suggested in two recent studies describing gene upregulation in pancreatic β cells and the detection of IL32 transcripts preceding the onset of autoantibodies in type 1 diabetes." (PMID 34262563, 2021). "This early increase in IL-32 might be an early biomarker for detecting abnormal immune function before type 1 diabetes becomes clinically apparent." (PMID 41340965, 2025). "The role of IL-32 in type 1 diabetes is still unclear, but it is possible that IL-32 might be crucially involved in the pathogenesis of autoimmune diabetes." (PMID 35122482, 2022).
endothelial dysfunction (7 papers, 2017 to 2026). In vascular diseases, endothelial dysfunction is a systemic pathological state of the endothelium (the inner lining of blood vessels) and can be broadly defined as an imbalance between vasodilating and vasoconstricting substances produced by (or acting on) the endothelium. "IL-32, a proinflammatory cytokine, is elevated in RA patients and plays a significant role in inflammation and endothelial dysfunction, both of which contribute to atherosclerosis." (PMID 40299461, 2025). "Interleukin 32 (IL32) alternative splicing produces isoforms (beta) that are involved in insulin resistance, endothelial dysfunction, hepatic fat accumulation, and fibrogenesis, whereas (gamma) isoforms are involved in inflammation." (PMID 40438258, 2025). "Given the prominent role of IL-6 in endothelial cell dysfunction and the specific upregulation of IL-6 by CAEC in response to IL-32 we aimed to determine the impact of the IL-32 isoforms on the typical endothelial dysfunction markers ICAM-I and VCAM-I." (PMID 36992409, 2023). "IL-32’s interplay with TNF-α and other inflammatory mediators is known to drive synovial inflammation and endothelial dysfunction, both of which could further heighten CV risk in this patient population." (PMID 40299461, 2025). "Pulmonary and arterial hypertension share as pathophysiological mechanism endothelial dysfunction, thickening of arterial vessels and smooth muscle cells contraction, as well as high levels of secreted IL32, which have been observed in these pathophysiological conditions." (PMID 37108628, 2023). "IL-32 also is up-regulated in KCs by IL-1β; this cytokine may induce vascular inflammation and endothelial dysfunction." (PMID 28323859, 2017). "Proinflammatory cytokine IL-32 is increased in RA and SLE, where it affects atherosclerotic plaque instability and endothelial dysfunction." (PMID 40937212, 2025). "IL-32 contributes to vascular inflammation by inducing IL-6 and TNF-α, enhancing endothelial dysfunction and pro-atherogenic lipid changes." (PMID 40937212, 2025). "A subset of the COVID patient cohort was tested for pro-inflammatory biomarkers: IL-32 displayed an inverse correlation with patients' neutrophil-to-lymphocyte ratio (NLR) (estimate -0.23 ± 0.81; p=0.005) and not with IL-6 and biomarkers of endothelial dysfunction (n=42, p=NS)." (PMID 41727490, 2026).
esophageal squamous cell carcinoma (7 papers, 2020 to 2024). Esophageal squamous cell carcinoma (ESCC) is a type of esophageal carcinoma (EC) that can affect any part of the esophagus, but is usually located in the upper or middle third. "Previous studies have found that IL-32 could be detected in esophageal squamous cell carcinoma (ESCC) immortalized cell lines." (PMID 34414188, 2021). "The recent publication evaluated the expression of IL-32 in different immune cells from esophageal squamous cell carcinoma (ESCC) by single-cell RNA sequencing found that IL-32 may have a paradoxical effect." (PMID 35281008, 2022). "In esophageal squamous cell carcinoma (ESCC), IL-32 internalized by macrophages leads to the polarization of M2 macrophages through the FAK-STAT3 pathway, thereby promoting lung metastasis of ESCC." (PMID 37415241, 2023). "In this study, we applied bioinformatics to analyze single-cell RNA sequencing data about tumor-infiltrating immune cells from esophageal squamous cell carcinoma (ESCC) TME and analyzed IL-32 expression in different immune cell types." (PMID 34414188, 2021).
Sepsis (7 papers, 2010 to 2025). Sepsis is defined as life-threatening organ dysfunction caused by a dysregulated host response to infection. "The potential role of IL-32 in the increased mortality risk of sepsis patients with chronic liver disease remains unclear." (PMID 40149726, 2025). "Intriguingly, IL-32 isoforms have opposing effects on sepsis, with IL-32γ associated with protection and IL-32β associated with increased severity; potentially associated with contrasting anti-inflammatory functions of IL-32." (PMID 40826444, 2025). "This study investigates whether plasma IL-32 is associated with sepsis severity and clinical outcomes." (PMID 40149726, 2025). "In addition to our findings on vascular inflammation and sepsis, IL-32 has been implicated in inflammatory diseases." (PMID 20221440, 2010). "Notably, higher IL-32 levels in SIRS/sepsis patients were associated with increased mortality." (PMID 40149726, 2025). "In our study, plasma IL-32 levels were significantly higher in SIRS/sepsis patients with liver cirrhosis." (PMID 40149726, 2025). "When patients with liver cirrhosis were excluded, the remaining 152 patients with SIRS/sepsis had significantly lower IL-32 levels than the healthy controls (p = 0.015)." (PMID 40149726, 2025). "After excluding these patients, IL-32 levels were lower in SIRS/sepsis patients compared to the controls." (PMID 40149726, 2025). "Within the SIRS/sepsis cohort, IL-32 plasma concentrations remained similar across patients diagnosed with SIRS, sepsis, and septic shock, whose disease severity increases in this order." (PMID 40149726, 2025). "In the early stages of sepsis, NK cells become activated and release various cytokines, including IL-32, which can exacerbate inflammation and contribute to tissue damage." (PMID 40149726, 2025). "This study identified a reduction in plasma IL-32 levels in patients with SIRS/sepsis compared to the healthy controls." (PMID 40149726, 2025). "Median IL-32 levels in patients with SIRS/sepsis and liver cirrhosis were 0.9 ng/mL (range: 0.1–10.0 ng/mL), comparable to those in the control group (0.7 ng/mL; range: 0–19.2 ng/mL; p > 0.05)." (PMID 40149726, 2025). "This study demonstrated that plasma IL-32 levels are lower in patients with SIRS/sepsis compared to the healthy controls." (PMID 40149726, 2025). "IL-32 promotes angiogenesis propagating vascular inflammation and exacerbates sepsis in a mouse model." (PMID 25386048, 2014). "In a mouse model of sepsis, IL-32 was shown to potentiate peritonitis-induced elevations in serum levels of TNF-α and IL-1β, and overexpression of the IL-32β isoform led to reduced time to death." (PMID 21649914, 2011). "Together, our results reveal an important function of IL-32 in vascular inflammation and sepsis development." (PMID 20221440, 2010). "While lymphopenia is associated with increased mortality, higher IL-32 levels were observed in non-surviving SIRS/sepsis patients." (PMID 40149726, 2025). "Plasma IL-32 levels were measured in 186 patients with SIRS/sepsis and 40 control subjects." (PMID 40149726, 2025). "Given that T cells are a primary source of IL-32, the lymphopenia observed in sepsis may contribute to the reduced systemic IL-32 levels." (PMID 40149726, 2025). "Plasma IL-32 levels were lower in patients with SIRS/sepsis compared to healthy controls." (PMID 40149726, 2025). "Thus, IL-32 has been reported to exacerbate sepsis in the cecal-ligation and puncture (CLP) mouse model, via propagating vascular inflammation." (PMID 36776839, 2023). "Our results reveal an important function of IL-32 in vascular inflammation and sepsis development." (PMID 20221440, 2010). "Here, we report a new function of IL-32 in vascular inflammation and sepsis development." (PMID 20221440, 2010). "In particular, IL-32 expression is enhanced after engagement of TLR4 receptors by ligands, including LPS, that play a major initiating role in ALI due to sepsis, hemorrhage, trauma, or hyperoxia." (PMID 21649914, 2011).
Sepsis (continued). "Plasma IL-32 levels were elevated in the 28 non-surviving patients (27 patients with septic shock and 1 patient with sepsis excluding those with cirrhosis) compared to the survivors." (PMID 40149726, 2025). "In patients with SIRS/sepsis, plasma IL-32 levels showed a significant negative correlation with age (correlation coefficient r = −0.219, p = 0.007)." (PMID 40149726, 2025). "In contrast, patients with SIRS/sepsis without liver cirrhosis had lower plasma IL-32 levels, with a median of 0.4 ng/mL (range: 0–12.0 ng/mL)." (PMID 40149726, 2025). "In the group of SIRS/sepsis patients with liver cirrhosis, 14 patients did not survive, but the serum IL-32 levels of survivors and non-survivors were similar (p > 0.05)." (PMID 40149726, 2025). "The area under the receiver operating characteristic (AUROC) curve was 0.681 (p = 0.003), indicating that IL-32 is an acceptable but not an excellent marker for distinguishing between surviving and non-surviving patients with sepsis/septic shock." (PMID 40149726, 2025). "While these findings suggest that IL-32 may not directly influence survival in cirrhotic patients with sepsis, the small sample size limits definitive conclusions." (PMID 40149726, 2025). "However, in our SIRS/sepsis cohort, plasma IL-32 levels did not correlate with inflammatory markers or immune cell counts." (PMID 40149726, 2025). "However, patients with SIRS/sepsis and liver cirrhosis (n = 34) had significantly higher IL-32 levels compared to SIRS/sepsis patients without cirrhosis (p = 0.002)." (PMID 40149726, 2025).
tuberculosis (7 papers, 2018 to 2025). A chronic, recurrent infection caused by the bacterium Mycobacterium tuberculosis. "Effective T cells play a crucial role in anti-tuberculosis immunity, and previous studies have reported an association between IL-32 and T cells." (PMID 38803498, 2024). "Therefore, additional research is imperative to uncover the mechanisms of IL-32 and its splice variants in tuberculosis." (PMID 38803498, 2024). "The IL-32 mRNA in active tuberculosis patients was lower than that in healthy individuals (all p < 0.05)." (PMID 38803498, 2024). "Different IL-32 isoforms have different effects and regulation patterns in anti-tuberculosis treatment." (PMID 38675618, 2024). "Understanding the production of IL-32 is crucial for enhancing our comprehension of the immune system and exploring new diagnostic and treatment strategies for conditions like TPE and tuberculosis." (PMID 38803498, 2024). "IL-32 expression was significantly upregulated in the lung tissues of patients with tuberculosis and can induce macrophage apoptosis, a vital killing mechanism of intracellular Mtb." (PMID 35880892, 2022). "For instance, T cells in lung tissue in IL-32γ-transgenic mice infected with Mtb expressed higher levels of interferon gamma (IFN-γ) and TNF-α, and IL-32 was correlated with the balance of TH1/TH17 cytokines in the peripheral blood of tuberculosis patients." (PMID 35880892, 2022). "Interleukin (IL)-15 and IL-32 play roles in the vitamin D-mediated tuberculosis (TB) defense mechanism." (PMID 30760247, 2019). "With the treatment of tuberculosis, the level of IL-32 gradually returned to normal." (PMID 38675618, 2024). "Based on previously published studies, these data further confirmed that IL-32 and different IL-32 isoforms had very different roles and regulatory patterns in the tuberculosis process, forging a strong basis for measuring different IL-32 isoforms in future laboratory and clinical studies." (PMID 38803498, 2024). "Thus, the current study provides novel insight into the role of IL-32 in the tuberculosis microenvironment." (PMID 35880892, 2022). "Therefore, this study provides new insights into the role of IL-32 in the tuberculosis microenvironment." (PMID 35880892, 2022). "IL-32 is increasingly recognized as an important host molecule against tuberculosis." (PMID 30426023, 2018). "In this review, we highlight the proinflammatory properties of IL-32 and the mode of action of IL-32 in mycobacterial infections to inspire the development of novel immunity-based countermeasures and host-directed therapies against tuberculosis." (PMID 30426023, 2018). "However, few studies have been focused on IL-32 in tuberculosis patients." (PMID 38803498, 2024). "Additionally, we observed that IL-32 might regulate ADA expression in macrophages in the tuberculosis microenvironment." (PMID 35880892, 2022). "IL-32 expression was increased in surgically resected lungs of active TB patients, particularly in airway epithelial cells and granuloma macrophages, suggesting a protective role of IL-32 against in vivo M. tuberculosis infection." (PMID 30426023, 2018). "Furthermore, IL-32 may modulate ADA expression in the tuberculosis microenvironment." (PMID 35880892, 2022). "Our findings may be one of the reasons explaining the role of IL-32 in controlling the immune response of tuberculosis, indicating that IFN-γ/IL-32/TNF-α signaling axis may play an important role in the pathogenesis of tuberculosis." (PMID 38803498, 2024).
Crohn disease (6 papers, 2007 to 2024). A gastrointestinal disorder characterized by chronic inflammation involving all layers of the intestinal wall, noncaseating granulomas affecting the intestinal wall and regional lymph nodes, and transmural fibrosis. "Among the genes mutually reported by the previous three studies, NK4/IL-32 was recently recognized as a central mediator of Crohn's disease and associated with liver damage during HCV infection." (PMID 17222352, 2007).
endometriosis (6 papers, 2020 to 2024). The growth of functional endometrial tissue in anatomic sites outside the uterine body. "When IL-32 was associated with CA-125, the specificity and sensitivity of this combination reached 60% and 82.9%, respectively, thereby suggesting IL-32 as a potential biomarker for endometriosis diagnosis." (PMID 32143439, 2020). "Interleukin 32 (IL-32) is a proinflammatory cytokine and an emerging, potential factor in the pathophysiology of endometriosis." (PMID 36428561, 2022). "In our previous study that used a cell culture and mouse model, high levels of IL-32 were identified in the peritoneal fluid of patients with endometriosis." (PMID 36428561, 2022). "This study revealed that the IL-32 concentration in the peritoneal fluid was drastically greater in patients of advanced-stage endometriosis as compared with the controls." (PMID 35281008, 2022). "In a study investigating the IL-32 effect in the pathogenesis of endometriosis as an example of stromal cancer, IL-32 showed a correlation in cancer progression." (PMID 35281008, 2022). "IL-32 possesses angiogenic properties and further studies are needed in order to clarify the mechanism in case of endometriosis, according to recent literature." (PMID 33435569, 2021). "Compared with the control group, the level of interleukin-32 (IL32) in peritoneal fluid (PF) in women with endometriosis was significantly higher." (PMID 34337010, 2021). "Moreover, IL-32 levels are reportedly elevated in the serum and peritoneal fluid of patients with endometriosis." (PMID 36428561, 2022). "The findings of this study suggest that DNG may reduce cell viability and proliferation in response to treatment with estrogen, TNF-α, IL-1β, or IL-32, and inhibit the pathogenesis of endometriosis by decreasing PCNA expression." (PMID 36428561, 2022). "Thus, DNG may reduce cell viability and proliferation induced by estradiol, TNF-α, IL-1β, and IL-32, and inhibit the endometriosis pathogenesis by decreasing PCNA expression." (PMID 36428561, 2022). "The markers related to the pathogenesis of endometriosis in ESCs were evaluated using estradiol, tumor necrosis factor alpha (TNF-α), interleukin 1β (IL-1β), and IL-32, administered alone or in combination with DNG." (PMID 36428561, 2022).
leprosy (6 papers, 2014 to 2024). Leprosy is a chronic infectious disease affecting primarily the skin and peripheral nervous system. "NOD2 recognition of MDP triggers the induction of specific inflammatory responses to combat bacterial infection, including the production of IL-32, which in leprosy is linked to host defense against the pathogen M. leprae." (PMID 27297389, 2016). "In leprosy, a human mycobacterial infection, IL-32 has been shown to promote the differentiation of monocytes into CD1b+ DCs upon NOD2 activation." (PMID 37727785, 2023). "IL-32 has been shown to be associated with the control and immunopathology of numerous infectious diseases including tuberculosis, HIV, leprosy, and hepatitis." (PMID 37727785, 2023). "Accordingly, the expression of NOD2 and IL-32, as well as the number of CD1b+ DCs were higher in tuberculoid than in lepromatous leprosy lesions, indicating a relevant mechanism to control the dissemination of infection." (PMID 37727785, 2023). "Moreover, the expression of endogenous IL-32 and NOD2 was increased in patients with the restrictive tuberculoid form of leprosy, which is caused by Mycobacterium leprae infection, suggesting that both NOD2 and IL-32 are associated with leprosy." (PMID 30426023, 2018). "The biological relevance of this pathway was demonstrated in leprosy, in which NOD2, IL-32, and CD1+ DC all were more highly expressed in skin lesions from patients with the self-limited tuberculoid (T-lep) form versus the progressive lepromatous leprosy (L-lep) form." (PMID 27297389, 2016). "IL-32 induction was measured, since it is specific to NOD2 versus TLR2/1 activation and is required to induce CD1b+ DC differentiation and cross-presentation, and its expression at the site of disease correlates with the self-limited versus progressive form of leprosy." (PMID 27297389, 2016).